HMGB1 (high mobility group box 1)
Diseases named in the same sentence as HMGB1 in open-access papers (continued):
Sharing a sentence is not in itself a finding about the gene and the disease.
cancer (continued). "In BxPC-3 cancer cells single treatment with TLR agonists either alone or in combination resulted in increased phosphorylation of Erk (ODN: relative optical density, ROD = 149%, LTA: 118%, LPS: 133%, HMGB1: 144%, ODN + HMGB1: 126%, LTA + HMGB1: 110%, and LPS + HMGB1: 113%) (left)." (PMID 27941651, 2016). "The genes MAPK3, HMGB1, HMGA1, PIK3CA, and MCL1 are genes known to stimulate cellular growth; however, contrary to what is normally reported in humans, in the present study these genes were shown to be consistently expressed at lower levels in malignant tumors." (PMID 27657059, 2016). "In addition to calreticulin exposure, late apoptotic or necrotic release of HMGB-1 from dying cells, and subsequent binding to TLR-4 on dendritic cells was necessary to obtain optimal antigen presentation of chemotherapy or radiotherapy treated cancer cells." (PMID 25688334, 2015). "Therefore, we deduce that exogenous HMGB1 binds to RAGE and initiates MEK/ERK signal transduction, a process that may play a crucial role in cancer cell survival and resistance to chemotherapy." (PMID 25652880, 2015). "First, HMGB1 translocates to the cytoplasm following several autophagic stimuli (e.g., hydrogen peroxide, rapamycin, and starvation), which in turn promotes autophagy through direct interaction with BECN1 to dissociate it from BCL2 in immortalized mouse embryonic fibroblasts and cancer cells." (PMID 25126737, 2014). "Moreover, cancer cells killed by Dox exposure released HMGB1 into the culture media and the level was again increased in a concentration-dependent manner.BCF-CM-pretreated cancer cell cultures showed less cell death in response to Dox than cells pre-treated with NTF-CM." (PMID 25512109, 2014). "Because there are no known tools differentiating secreted HMGB1 between immune cells and cancer cells, we couldn't discriminate the source of HMGB1 secretion in our clinical samples." (PMID 22496788, 2012). "Additionally, HMGB1 (High-Mobility Group Box 1) and ADAM9 (A Disintegrin and Metalloproteinase 9) are upregulated in PC and verified as targets for miR-129-5p across digestive malignancies implying more extensive anti-cancer actions and pending additional functional studies in PDAC70,71." (PMID 40730640, 2025). "Thus, different forms of HMGB1 (oxidized or reduced) have different effects on MSCs and may have a different impact on cancer cells within TME; however, the mechanism is not completely elucidated." (PMID 39940960, 2025). "Therefore, HMGB1 released from necrotic cells during chemotherapy may stimulate (through RAGE) the proliferation of the remnant cancer cells and metastasis contributing to the resistance to cancer therapy." (PMID 39830522, 2024). "Interestingly, the outcome of HMGB1 treatment might be quantitatively and qualitatively linked to PKM1/2 expression as the latter isoform is expressed in many types of cancer cells but not in their normal cellular counterparts." (PMID 35887213, 2022). "Thus, this compound may be a useful tool for understanding the functional role for HMGB1-RAGE signaling in linking inflammation to carcinogenesis and provide a novel scaffold for the development of a new type of anti-cancer drug possessing anti-inflammatory activity." (PMID 33805209, 2021). "Furthermore, HMGB1 and RAGE interaction activates MAPK signaling pathway through K-Ras, Rac1/JNK/SAPK, and ERK1/2/Drp1 phosphorylation and prompts CRC progression, chemoresistance and regrowth of cancer cells, and colonic myofibroblast proliferation, migration, and invasion." (PMID 33117687, 2020). "However, the mechanism by which HMGB1 expression is elevated in cancers is not clear." (PMID 29728635, 2018). "However, extracellular HMGB1 is known to act as a growth factor that activates mitogen-activated protein kinase (MAPK) and thereby enhances the regrowth, metastasis, and chemoresistance of remnant cancer cells that survived prior chemotherapy via RAGE15,19,39–43." (PMID 30258050, 2018).
cancer (continued). "However, certain cancers such as adrenal gland carcinoma contain no HMGB1 protein." (PMID 28969092, 2017). "One reason for this could be that cancer cells operating without oxygen have to switch between low (supplying anabolic pathways, i.e., pentose phosphate shunt) and high (fueling anaerobic energy metabolism) PK activity and HMGB1 would impair this plasticity." (PMID 27652323, 2016). "The objective of this study is to better understand the role of HMGB1 and HMGB2 in aggressive PCa cancers not responding to hormonal treatment, identifying genes differentially regulated." (PMID 38542079, 2024). "This compound can induce ICD in cancer cells by affecting the expression of DAMPs, such as HSP70, HSP90, and HMGB1, without affecting the expression of CRT." (PMID 37705051, 2023). "We found that the combined treatment with radiation and ATR inhibitors can increase the release of HMGB1 and secretion of ATP, but not surface-presentation of CALR, in several human cancer cell lines." (PMID 37346039, 2023). "Unlike HMGB1, IFNA1, IFNA2, IL-2, KIR2DL3, IL-13 and NCAPG2 demonstrated an intuitive correlation in only a few cancer types." (PMID 36776838, 2023). "Although for most S100s, and for HMGB1, the transcript levels were lower in the control HPNE cells than in the cancer cell lines, this was not the case for S100A4, S100A6, S100A7, S100A12, and S100A13." (PMID 37627239, 2023). "In fact, BoxA does induce the release of calreticulin and HMGB1; remarkably, though, BoxA does not induce cell death, which by itself excludes ICD as a possible mechanism of anti-cancer immunity." (PMID 34561422, 2021). "Assessing putative cell surface receptors (TLR2 and TLR4) binding with extracellular HMGB1, we found that TLR2, but not TLR4, was upregulated in the CD133− cancer cells when treated with HMGB1+ irradiation cells or rhHMGB1." (PMID 31558702, 2019). "A recent report indicates that interactions between EphA4 on cancer cells and ephrin on macrophages leads to a CSC state for cancer cells without stimulation by external ligands such as LPS and HMGB1." (PMID 28969049, 2017). "Here, our results show that the expression of HMGB1 is higher in NSCLC tissues than healthy non-cancer control tissues, leading to poor prognosis and correlating with cancer TNM stages." (PMID 26840258, 2016). "Attractively, exposure to H2O2 made HMGB1 inactive, both as inducers for VEGF-A secretion and EC migration; however, H2O2 failed to prevent angiogenesis of ECs cultured in cancer CM." (PMID 26099505, 2015). "Extracellular HMGB1 binds to the ‘receptor for advanced glycation end products’ (RAGE), in cancers but not normal tissues." (PMID 25512109, 2014). "First, HMGB1 is acutely translocated and secreted by immune cells in response to TNF-α, IL-1β, or LPS stimulation, whereas cancer cells have no known stimuli for translocation and secretion." (PMID 22496788, 2012). "Although HMGB1 and its receptor, RAGE, are thought to be elevated in almost all types of cancer, recent studies have revealed that this is not true for all cases." (PMID 19476625, 2009). "Cancer and non-cancer cells with ferroptosis induced by the treatment of erastin, sorafenib, RSL3, and FIN56 could release the high mobility group box 1 (HMGB1), one of the DAMPs." (PMID 36926345, 2023). "In the absence of cancer-suppressive lncRNAs such as SEMA3B-AS1, HMGB1 cannot be recruited to play a vital role in DNA repair in time, but it may be transferred to the cytoplasm and extracellular space." (PMID 35273678, 2022). "DAMPs released during ICD comprise chaperones of endoplasmic reticulum (ER) such as heat-shock proteins (HSPs) and calreticulin (CALR), type I interferons (I-IFNs), non-histone chromatin-binding protein HMGB1, ATP, annexin A1 (ANXA1), and cancer cell-derived nucleic acids." (PMID 35488303, 2022).
cancer (continued). "Furthermore, although no binding activity was observed between HMGB1 and GlucoGL, which binds strongly to PGRMC1, GlucoGL exhibited a more potent anti-cancer effect in vitro and in vivo." (PMID 34209885, 2021). "No prior study has shown an effect of HMGB1 on MMP-2 and TIMP-3 whereas it has been recently reported that HMGB1 enhances MMP-9 expression in neurons, via Toll-Like Receptor 4 signaling, and in cancer cells via NF-κB signalling." (PMID 21731608, 2011). "Its role in HMGB1 and RAGE signaling in cancer has not been fully explored." (PMID 21087493, 2010). "Although the proteins identified in the study, as well as HMGB1 and HMGB2, had been previously and independently related to EOC, the implication of a direct interaction with HMGB proteins, as part of their mechanism of action in cancer progression, had not been previously envisaged." (PMID 32867128, 2020). "It was reported that ferroptosis cancer cells and non-cancer cells could release HMGB1, and then activate co-cultured BMDMs (bone marrow-derived macrophages) to secrete proinflammatory cytokine tumor necrosis factor alpha (TNF-α) via the HMGB1-AGER signaling pathway." (PMID 37325669, 2023). "Thus, the nuclear abundance of HMGB1 (and likely also of HMGB2) can be seen as a marker for proliferative capacity: Senescent cells have essentially no nuclear HMGBs, while continuously dividing cancer cells display levels even higher than those seen in normal tissue." (PMID 34166567, 2021).
infection (425 papers, 2007 to 2026). The state of being infected such as from the introduction of a foreign agent such as serum, vaccine, antigenic substance or organism. "Concurrently, infection-induced epithelial cell death results in the release of damage-associated molecular patterns (DAMPs), such as high-mobility group box 1 (HMGB1), which further activate immune cells and intensify the inflammatory milieu." (PMID 41278223, 2025). "Extensive investigations have shown that HMGB1 plays a critical role in infection and injury associated with the onset of inflammation." (PMID 39682695, 2024). "Pyroptosis is characterized as cellular inflammatory and lytic cell death that occurs upon infection with intracellular pathogens and results in the release of several damage-associated molecular patterns, such as HMGB1 and inflammatory cytokines." (PMID 37071849, 2023). "In contrast, extracellular HMGB1 has been found to be a mediator of both sterile inflammation and infection associated responses, which can induce proinflammatory cytokine release from cells." (PMID 35573828, 2022). "Infections and treatment-associated toxicity should be considered when interpreting the dynamics of HMGB1." (PMID 34671818, 2022). "Concurrently, elevated serum HMGB1 levels appear to be clearly associated with sterile inflammation and infection." (PMID 36712653, 2022). "HMGB1, infection, and Child-Pugh score are considered to be independent risk factors for 90-day adverse clinical outcomes of AKI among HBV-ACLF patients." (PMID 36712653, 2022). "HMGB1 is a damage-associated molecular pattern protein that is released from the nucleus to the extracellular space during inflammation and infection." (PMID 35983056, 2022). "In mammalian cells, HMGB1 is a highly conserved nuclear protein implicated in several gene regulations, including inflammation and infection-related genes." (PMID 35201494, 2021). "It has been reported that high plasma HMGB1 levels in patients with ATL are caused by infection with human T cell lymphotropic virus type I (HTLV-I)." (PMID 32660524, 2020). "The extracellular HMGB1 has been established as a pathogenic mediator of both infection- and injury-elicited inflammatory diseases." (PMID 29447234, 2018). "Serum HMGB1 levels were measured by an enzyme-linked immunosorbent assay (ELISA) prior to infection until day 14 or 18 post-infection." (PMID 29535197, 2018). "Serum samples were collected from all animals before and 2, 4, 6, 8, 10, 14, and 18 days post-infection (p.i.)to measure the concentration of HMGB1 in an enzyme-linked immunosorbent assay (ELISA)." (PMID 29535197, 2018). "High mobility group box 1 (HMGB1) is a damage-associated molecular pattern (DAMP) protein that mediates inflammatory responses after infection or injury." (PMID 29447234, 2018). "HMGB-1 is a late-phase cytokine, which is released extracellularly in response to systemic inflammation caused by infection, shock, or trauma." (PMID 29249869, 2017). "Pathogenic infection triggered the release of HMGB1, a proinflammatory factor released by necrotic cells." (PMID 27929533, 2016). "A persistent elevation of TNF-α and HMGB-1 can induce a further infiltration of neutrophils and macrophages to the site of infection, which cause an uncontrolled HIR." (PMID 27556404, 2016). "The disruption of local expression of HMGB1 renders animals susceptible to infectious or injurious insults, reinforcing a beneficial role of intracellular HMGB1 in immunity against infection and injury." (PMID 25821489, 2015). "Here, we utilized biopsies from patients with skin and STIs caused by S. pyogenes to assess the presence of HMGB1 at the local infected site of infections characterized by inflammation and necrosis." (PMID 24524027, 2014). "Increased HMGB1 expression has been linked to infection progression by interfering with several signaling pathways, especially the autophagy pathway." (PMID 24923305, 2014).
infection (continued). "In this study, HMGB1 release was modulated by Plasmodium infection and increased in the peripheral blood of ECM-susceptible mice following infection, similar to observation in human populations, suggesting a potential role for HMGB1 in disease progression." (PMID 23506269, 2013). "High mobility group box 1 (HMGB1), a DNA-binding nuclear protein, has been implicated as an endogenous danger signal in the pathogenesis of infection diseases." (PMID 23359306, 2013). "Infection of A549 alveolar epithelial cells with L. pneumophila caused programmed cell death, activation of various caspases, and release of HMGB1." (PMID 18447956, 2008). "• The 982C>T exon 4 polymorphism was associated with significantly lower levels of serum HMGB1, and with significantly higher probability of early death due to infection." (PMID 18577209, 2008). "Infection of A549 alveolar epithelial cells by L. pneumophila caused cell death, nuclear DNA fragmentation, activation of various caspases, and release of HMGB1." (PMID 18447956, 2008). "We show herein that HAdV-D37 infection of both immortalized and primary corneal epithelial cells is associated with HMGB1 acetylation, CRM1-dependent nuclear-to-cytoplasmic translocation, and LAMP1-mediated release of into cell supernatants, in contrast to infection of the same cells by HADV-C5." (PMID 40367285, 2025). "Depending on the virus type, HMGB1 may associate with viral proteins or genomes to promote the infection, or in contrast, HMGB1 may stimulate the interferon response to restrict virus replication." (PMID 39611842, 2025). "HMGB1, which is a protein that is found in large quantities in chromosomes, acts as a damage-associated molecular pattern that initiates innate inflammatory responses against infection and injury." (PMID 38716542, 2024). "However, this study did not include subjects with pathological states causing high serum HMGB-1, such as asphyxia, severe infection, and fetal inflammatory response syndrome." (PMID 37649540, 2023). "Indeed, it has been found that high levels of HMGB1 due to infection-mediated stimuli is associated with a higher risk of adverse pregnancy outcomes, such as PPROM and preterm birth." (PMID 38260915, 2023). "However, much remains to be investigated with respect to the role of fish HMGB1 as a stress-induced DAMP in association with pathogen infection." (PMID 36140677, 2022). "Importantly, the risk of 90-day adverse outcomes increased with higher HMGB1 values (p-value for trend = 0.004) in Model IV adjusted for age, infection, and CLIF-C ACLF." (PMID 36712653, 2022). "In addition, a study on the MG-Rlow strain showed that MG-Rlow infection upregulated HMGB1 expression and activated the TLR4 signaling pathway, causing severe lung injury and intestinal flora imbalance in chickens." (PMID 36139393, 2022). "Furthermore, our results provide a novel theoretical reference for comprehension of HMGB1 aggravating pathogenic infections and pathogenesis." (PMID 36139393, 2022). "Loss of the pro-inflammatory cytokine functions of HMGB1 may increase the risk of infection and lead to autophagy deficiency, contributing to inflammation." (PMID 33187536, 2020). "In IRF7-/- mice, the peak of infection (7 dpi) was associated with increased nuclear-to-cytoplasmic HMGB1 translocation in the epithelium, increased IL-33 levels in the airway lumen, and the infiltration of neutrophils, which can process IL-33 to a more biologically active form." (PMID 32658914, 2020). "We suspect that HMGB1 and IL-1β bind in vesicles as they are packaged for secretion; however this needs to be elucidated further and we predict that MV/HMGB1 levels will correlate with poor patient outcome, increased immune dysfunction and infection susceptibility in a large cohort of patients." (PMID 29601597, 2018). "HMGB1 is a key mediator of inflammation during sterile- and infection-associated responses." (PMID 29967293, 2018).